MIR31HG (MIR31 host gene)
Diseases named in the same sentence as MIR31HG in open-access papers (continued):
Sharing a sentence is not in itself a finding about the gene and the disease.
cancer (continued). "MIR31HG has been found dysregulated in human cancers and can regulate the cell proliferation positively or negatively." (PMID 30180891, 2018). "MIR31HG is deleted in numerous cancers but deletions occur most frequently in GBM, exceeding 73% of all GBMs." (PMID 26164206, 2015). "MIR31HG is dysregulated in many cancers but MIR31HG deletions are most profound in GBM (>73% all GBM)." (PMID 26164206, 2015). "The expression, related functions, clinical features and related genes of MIR31HG in cancers." (PMID 37636269, 2023). "Differential expression of MIR31HG in specific tissues in cancers helps to distinguish diseased tissues from normal tissues, indicating that MIR31HG could be a potential biomarker for early cancer diagnosis." (PMID 37636269, 2023). "These clinical features elucidate the possibility that MIR31HG could serve as a prognostic biomarker in human cancer." (PMID 37636269, 2023). "A study in 2012 also assumed that there could be a large CPG island in its promoter, and showed the role of MIR31HG in promoting hypermethylation in human cancer." (PMID 37636269, 2023). "In addition to its role in cancer, MIR31HG also plays a role in adipocyte differentiation (adipogenesis)." (PMID 35743003, 2022). "One cancer-associated gene (MPHOSPH8) was upregulated in samples infected with M.BCG relative to those infected with P.BCG, whereas three genes were downregulated in M.BCG (MIR31HG, SAA1, and TRIML2)." (PMID 35562916, 2022). "It would be interesting to explore whether such phenomena also exist in PDAC and the involving role of MIR31HG in cancer cell-adipocyte trans-differentiation in the future." (PMID 35743003, 2022). "Besides, abnormal expression of MIR31HG was deemed as potential biomarker to reflect the clinicopathological characteristics and prognostic outcomes of cancer patients." (PMID 32280307, 2020). "MIR31HG has been reported to affect cell proliferation in various cancers." (PMID 30180891, 2018). "Notably, MIR31HG expression was significantly increased in MIR31HG diploid and amplified cancer tissues, indicating that the upregulation of MIR31HG expression was significantly correlated with MIR31HG copy number amplification and CDKN2A‐CDKN2B‐MTAP deletion in a pan‐cancer sample." (PMID 35570408, 2022). "However, they found that MIR31HG knockdown was sufficient to upregulate mesenchymal markers and downregulate epithelial markers, suggesting that a cancer type-specific role of MIR31HG may exist." (PMID 35743003, 2022). "Interestingly, MIR31HG is downregulated in some cancers, such as esophageal squamous cell carcinoma, hepatocellular carcinoma, and bladder cancer, indicating that its function may be cancer type-specific." (PMID 40065368, 2025). "Our findings highlight the pivotal role of MIR31HG in regulating partial EMT, a state in which cancer cells exhibit both epithelial and mesenchymal traits, facilitating metastasis and therapy resistance." (PMID 40065368, 2025). "LUCAT1, UCA1, and MIR31HG were significantly increased in the cancer group (p < 0.05), particularly LUCAT1 and MIR31HG (p < 0.0001)." (PMID 36980216, 2023). "In vitro evidence demonstrated that TGFβ induced MIR31HG expression in PDAC cells, and knockdown of MIR31HG expression reversed TGFβ-induced EMT phenotypes and cancer cell migration." (PMID 35743003, 2022). "When the expressing construct was transfected into the two cancer cells, MIR31HG level was augmented by ~ 4-fold for SW579 cells and ~ 5-fold for TPC-1 cells, validating the MIR31HG upregulation efficacy of the construct." (PMID 35443670, 2022). "Therefore, the role of MIR31HG in cancers might be cancer type-specific." (PMID 35743003, 2022). "MIR31HG and SNHG3, both of which have been reported to play oncogenic role in other cancers, were 2.5- and 2.3-fold upregulated (P < 0.0002 and P < 0.0001), respectively." (PMID 32108138, 2020).
cancer (continued). "Further, there is evidence showing that it was upregulated in oncogene-induced senescence process; and knockdown of MIR31HG induced a tumor suppressor p16INK4A dependent senescence phenotype, which might link it to HPV-related cancer carcinogenesis." (PMID 28415559, 2017). "Here we identify MIR31HG as a hypoxia-inducible lncRNA and therefore we name it LncHIFCAR (long noncoding HIF-1α co-activating RNA); we describe its oncogenic role as a HIF-1α co-activator that regulates the HIF-1 transcriptional network, crucial for cancer development." (PMID 28639619, 2017). "Although MIR31HG is the host gene of microRNA (miR)-31 and their expressions are positively correlated in some cancers, knockdown of MIR31HG does not change the level of miR-31, suggesting that MIR31HG may function in cancers independent of miR-31." (PMID 35743003, 2022).
digestive system tumors (1 paper, 2022). "A meta-analysis suggested that overexpression of MIR31HG predicted poor survival and metastasis in respiratory system and digestive system tumors." (PMID 36060239, 2022).
infection (1 paper, 2022). The state of being infected such as from the introduction of a foreign agent such as serum, vaccine, antigenic substance or organism. "Overall, the differential expression of MPHOSPH8, MIR31HG, SAA1 and TRIML2 could show us the subtle changes that occur in the infection between M.BCG and P.BCG." (PMID 35562916, 2022).
MIR31HG also shares sentences with these, for which no sentence is quoted: esophageal squamous cell carcinoma (5 papers); lung squamous cell carcinoma (2); triple-negative breast carcinoma (2); bladder squamous cell carcinoma (1); bladder urothelial carcinoma (1); cervical cancer (1); cervical squamous cell carcinoma (1); colon adenocarcinoma (1); endocervical adenocarcinoma (1); hepatoblastoma (1); Hirschsprung disease (1); IgA nephropathy (1); metabolic disease (1); nasopharyngeal carcinoma (1); pancreatic adenocarcinoma (1); rectum adenocarcinoma (1); rheumatoid arthritis (1); sarcoma (1); stomach adenocarcinoma (1).